BRAF (B-Raf proto-oncogene, serine/threonine kinase)
Diseases named in the same sentence as BRAF in open-access papers (continued):
Sharing a sentence is not in itself a finding about the gene and the disease.
metastatic colorectal cancer (continued). "The prognostic role of the V600E mutation of v-raf murine sarcoma viral oncogene homolog B1 (BRAF) in metastatic colorectal cancer (mCRC) is well established, but the therapeutic regimen targeting this disease is lacking." (PMID 29037218, 2017). "The BRAF V600E mutation is negatively associated with prognosis in patients with metastatic colorectal cancer (mCRC), distinguishing them as a subgroup that obtains modest benefit from standard treatments." (PMID 29037218, 2017). "BRAF activation mutations (most commonly V600E) occur in less than 10% of metastatic colorectal cancer and are associated with poorer survival." (PMID 28993799, 2017). "Approximately 5-10% of metastatic colorectal cancers harbor a BRAF-V600E mutation, which is correlated with resistance to EGFR-targeted therapies and worse clinical outcome." (PMID 26160848, 2015). "Among 389 samples from 141 patients suffering from metastatic colorectal cancer (mCRC), we found 22 samples from seven different patients to be BRAF V600E mutated by Sanger sequencing." (PMID 25318602, 2015). "RAS and BRAF mutations impact treatment and prognosis of metastatic colorectal cancer patients (mCRC), but the knowledge is based on trial patients usually not representative for the general cancer population." (PMID 26121270, 2015). "Accordingly, BRAF mutations observed in metastatic colorectal cancer patients are associated with a dramatic increase in mortality, compared to those with tumors with wild-type BRAF." (PMID 26160848, 2015). "BRAF mutation has been investigated as a prognostic factor in metastatic colorectal cancer (mCRC) undergoing anti-EGFR monoclonal antibodies (moAbs), but current results are still inconclusive." (PMID 23776587, 2013). "In a retrospective study of sporadic metastatic colorectal cancer (mCRC), BRAF mutations, detected in 8% of patients, were emerged as an independent prognostic factor for both progression-free survival (PFS) and overall survival (OS)." (PMID 20485284, 2010). "We address the prognostic and predictive value of KRAS, PIK3CA and BRAF mutations for clinical outcomes in response to active agents in the treatment of metastatic colorectal cancer (mCRC)." (PMID 19603024, 2009). "BRAF mutation is present in about 5–15% of metastatic colorectal cancer (mCRC)." (PMID 41225509, 2025). "Mutations affecting the BRAF gene were present in approximately 8–12% of metastatic colorectal cancer; BRAF is a key driver gene of mitogen-activated protein kinase (MAPK) activation, and its mutations are associated with a poorer response to standard treatments and worse prognosis." (PMID 41440935, 2025). "However, in cancers like metastatic colorectal cancer, BRAF mutations are associated with poor outcomes due to aggressive disease behavior and resistance to conventional chemotherapy." (PMID 40332392, 2025). "Increasing evidence indicates that mutations in the BRAF oncogene are not only tied to a poorer prognosis but also correlate with reduced efficacy of anti-epidermal growth factor receptor antibodies in treating metastatic colorectal cancer (mCRC)." (PMID 39119381, 2024). "Thus, ∼10% of metastatic colorectal cancer (mCRC) harbor a BRAF V600E mutation, associated with a poor prognosis and a limited response to systemic historical treatments in mCRC." (PMID 39255538, 2024). "Hence, the BEACON CRC trial combined encorafenib, cetuximab, and binimetinib and demonstrated that the combination was clinically efficacious, extended OS, and improved responses in patients with metastatic colorectal cancer and BRAF V600E mutations." (PMID 36801912, 2023). "BRAF mutation occurs in 5%–10% of metastatic colorectal cancers (mCRCs)." (PMID 36912150, 2023). "Thus, a recent study has shown that the 3-year overall survival rates for BRAFV600E-mutated and BRAF wild-type metastatic colorectal cancer patients were 54% and 82.9%, respectively." (PMID 37629086, 2023).
metastatic colorectal cancer (continued). "Thus, the encorafenib with cetuximab doublet is the preferred second line treatment for metastatic colorectal cancers with V600E BRAF mutations." (PMID 36079062, 2022). "In addition, in metastatic colorectal cancer patients participating in four trials, BRAF mutations were associated with worse PFS and OS in MMR proficient but not in MMR deficient cancers." (PMID 36079062, 2022). "BRAF mutations are present in approximately 10–15% of patients with metastatic colorectal cancer." (PMID 36339570, 2022). "Combining BRAF and MEK inhibitors (encorafenib and binimetinib) with the anti-EGFR antibody, cetuximab, results in higher responses and a significantly longer overall survival compared with standard therapy in patients with metastatic colorectal cancers with the V600E BRAF mutation." (PMID 35492830, 2022). "Patients with BRAF V600E mutated metastatic colorectal cancer (mCRC) have a poor prognosis." (PMID 36527039, 2022). "BRAF mutations (M0: 6.3%, M1: 21.4%; p = 0.019) are more frequent in patients with metastasis, and this is a higher frequency compared to previously reported 5-10% in metastatic colorectal cancer." (PMID 35003350, 2021). "Another recent study aimed to determine how KRAS, NRAS and BRAF mutations in hematopoietic cells may alter the results of liquid biopsies in patients with metastatic colorectal cancer." (PMID 35127745, 2021). "Efficacy of conventional chemotherapies for BRAF-mutated metastatic colorectal cancer." (PMID 33842313, 2021). "Somatic BRAF mutations occur in approximately 10% of metastatic colorectal cancers (mCRCs)." (PMID 33925278, 2021). "Thus, the aim of this study is to evaluate the role of KRAS and BRAF mutations as prognosis factors and predictive biomarkers for 1st line standard chemotherapy in metastatic colorectal cancer." (PMID 31952366, 2020). "Studies have shown that the prevalence of RAS and BRAF mutations may differ by tumor sidedness among metastatic colorectal cancer (mCRC) patients." (PMID 31856410, 2020). "Immunotherapy for patients with microsatellite‐instable (MSI‐H) tumors or BRAF‐inhibitors combination treatment for BRAF‐mutated (mutBRAF) tumors in metastatic colorectal cancer (mCRC) is promising, but the frequency of these molecular changes in trial patients are low." (PMID 31070306, 2019). "We assessed whether selection according to RAS/PIK3CA/BRAF mutational status could be beneficial for patients treated with bevacizumab as first-line treatment for metastatic colorectal cancer." (PMID 28068936, 2017). "Our objective was the determine the frequency of most common mutations in KRAS gene (p.G12D, p.G12V, p.G12A, p.G12C, p.G12S, p.G12R, p.G13D, p.Q61H, p.Q61L, p.Q61R, p.A146T, p.A146V, p.A146P) together with the BRAF V600E mutation in Albanian patients with metastatic colorectal cancer." (PMID 25267307, 2014). "Our aim was to investigate the prognostic and predictive value of the oncogenic MAPKK-like protein T-cell-originated protein kinase (TOPK) stratified by KRAS and BRAF mutations in patients with sporadic, hereditary and metastatic colorectal cancer (CRC) treated with anti-EGFR therapy." (PMID 19935791, 2010). "The second and major part of our study was to investigate whether therapy-related resistance due to acquired second KRAS/BRAF mutations also occurs in metastatic colorectal cancer after anti-EGFR therapy." (PMID 20300583, 2009). "However, the specific relationship among gut microbiome, metabolite profiles, and mutated-RAS/BRAF metastatic colorectal cancer (M-mCRC) remains unclear." (PMID 39046546, 2024).
metastatic colorectal cancer (continued). "Moreover, in some patients with metastatic colorectal cancer with the BRAF V600E mutation, the combination of encorafenib, cetuximab, and binimetinib significantly prolonged overall survival and demonstrated a high response rate compared to the standard therapy." (PMID 36732357, 2023). "Therefore, anti-EGFR antibody treatment was only indicated when patients had no mutations in KRAS or BRAF until recently, combination treatment of cetuximab with encorafenib and binimetinib was approved for the treatment of patients with metastatic colorectal cancer harboring a BRAF V600 E mutation." (PMID 35035479, 2022). "However, it remains unknown whether RAS/PIK3CA/BRAF tumor mutations can predict the efficacy of bevacizumab in metastatic colorectal cancer." (PMID 28068936, 2017). "The combination of a BRAF inhibitor (BRAFi) together with an anti-EGFR inhibitor (EGFRi) represents a standard of care approach in BRAFV600E metastatic colorectal cancer (mCRC) patients." (PMID 41882736, 2026). "Patients with BRAF V600E-mutant metastatic colorectal cancer have poor prognosis, and the value of first-line targeted combination therapies remains uncertain." (PMID 41797900, 2026). "Cetuximab plus fluoropyrimidine every two weeks (Q2W) is a common maintenance approach for RAS/BRAF wild-type metastatic colorectal cancer, but is limited by infusion burden and schedule misalignment." (PMID 42032138, 2026). "MAPK-targeted approaches did not become an important part of the treatment armamentarium for metastatic colorectal cancer with BRAF V600E until the presentation of data from the BEACON trial." (PMID 41294686, 2025). "The inhibitor WNT974 was studied in combination with encorafenib and cetuximab in a phase Ib/II trial of patients with BRAF V600E mutated, KRAS wild type metastatic colorectal cancer." (PMID 40061138, 2025). "S CAPSTAN CRC, a retrospective, observational European study examined the treatments available for BRAF V600E-positive metastatic colorectal cancer treated over a 4-year period." (PMID 40977811, 2025). "Objective response rate (ORR) and disease control rate (DCR) among patients with BRAF V600E-mutant metastatic colorectal cancer receiving different first-line treatment strategies." (PMID 40761242, 2025). "Despite continuing improvement in the standard of care, the clinical outcomes in metastatic colorectal cancer (CRC) remain poor, especially among patients whose tumors carry activating mutations in BRAF or RAS-family oncogenes." (PMID 41465386, 2025). "The PANDA trial evaluates the efficacy of panitumumab combined with FOLFOX in patients over 70 years with RAS/BRAF wild-type metastatic colorectal cancer." (PMID 40805233, 2025). "Multivariate Cox regression analysis of prognostic factors for overall survival in patients with BRAF V600E-mutant metastatic colorectal cancer." (PMID 40761242, 2025). "Encorafenib + cetuximab (EC) is approved for previously treated BRAF V600E-mutant metastatic colorectal cancer (mCRC) based on the BEACON phase 3 study." (PMID 39863775, 2025). "In metastatic colorectal cancer (mCRC), KRAS and BRAF mutations are well-known markers of resistance and poor prognosis in patients receiving anti-epidermal growth factor receptor (EGFR) monoclonal antibodies." (PMID 40279317, 2025). "Microsatellite-stable metastatic colorectal cancer (MSS mCRC) is currently treated with chemotherapy and targeted agents based on RAS and BRAF mutational status." (PMID 41018484, 2025). "Cetuximab plus irinotecan, fluorouracil, and leucovorin (FOLFIRI) represents a first-line therapeutic standard for RAS/BRAF wild-type metastatic colorectal cancer (mCRC) patients." (PMID 40328753, 2025). "This nonrandomized controlled trial evaluates anti–epidermal growth factor receptor (EGFR) rechallenge therapy in patients in Italy with circulating tumor DNA (ctDNA) RAS/BRAF wild-type (wt) metastatic colorectal cancer." (PMID 38592721, 2024).
metastatic colorectal cancer (continued). "The conventional treatment strategies for patients with metastatic colorectal cancer (mCRC) are predominantly guided by the status of RAS and BRAF mutations." (PMID 38706918, 2024). "Ongoing clinical trials targeting specifically BRAF‐mutant metastatic colorectal cancer (mCRC) retrieved through a systematic review process performed on 10 April 2024." (PMID 39073010, 2024). "A combination of encorafenib (a BRAF inhibitor) and cetuximab (an EGFR inhibitor) has been shown in clinical trials to improve survival in patients with metastatic colorectal cancer harboring the BRAF V600E mutation." (PMID 38888919, 2024). "Therapeutic anti-EGFR moAbs (cetuximab and panitumumab) remain the mainstay of targeted therapy in RAS/BRAF wild-type metastatic colorectal cancer." (PMID 38711991, 2024). "For 50% of patients with KRAS/NRAS/BRAF wild-type metastatic colorectal cancer, the median survival after treatment is approximately 30 months." (PMID 38576495, 2024). "The present study underscores the significance of [18F] FDG PET-CT radiomic parameters, particularly SUVmax, in their association with KRAS, BRAF, and EGFR mutations in metastatic colorectal cancer patients." (PMID 39722096, 2024). "The combination of the anti-EGFR antibody cetuximab with irinotecan or the FOLFIRI regimen has improved treatment outcomes in RAS and BRAF wild-type metastatic colorectal cancers." (PMID 39033209, 2024). "The purpose of this study was to assess the ability of metabolic parameters, radiomic features, PET-CT, and clinicopathological data to detect EGFR, BRAF, and KRAS mutation status in metastatic colorectal cancer patients (mCRC)." (PMID 39722096, 2024). "BRAF and KRAS mutations have been reported to occur in ∼10% and 44% of patients with metastatic colorectal cancer, which is similar to frequency (KRAS: 46%; BRAF: 11.2%; NRAS: 3%) observed in our sample cohort." (PMID 37483495, 2023). "For instance, in a recent clinical trial, the addition of vemurafenib improved the progression-free survival in patients with BRAF-mutant metastatic colorectal cancer treated with irinotecan and cetuximab." (PMID 37719863, 2023). "Monoclonal antibodies targeting EGFR, either when combined with conventional cytotoxic chemotherapy, or as single agents, produce significant survival prolongation in patients with RAS and BRAF wild type metastatic colorectal cancer (mCRC)." (PMID 36352028, 2023). "In the multicentre randomised Phase II/III FOCUS4-D trial, 32 patients with metastatic colorectal cancers WT for BRAF, PIK3Ca, KRAS and NRAS after first line induction therapy were randomised 1:1 to either AZD8931 40 mg bd continuous dosing regimen vs placebo." (PMID 36352028, 2023). "Rechallenge with anti-EGFR drugs represents a promising strategy in refractory RAS/BRAF wild-type (WT) metastatic colorectal cancer (mCRC)." (PMID 37046778, 2023). "Rechallenge with epidermal growth factor (EGFR) inhibitors represents a promising therapeutic strategy in patients with refractory RAS/BRAF wild-type metastatic colorectal cancer (mCRC)." (PMID 37046778, 2023). "BRAF mutant metastatic colorectal cancer has long been considered a tumor with a poor prognosis and a poor response to chemotherapy." (PMID 37302081, 2023). "The BRAF gene, one of the key members in the mitogen‐activated protein kinase (MAPK) pathway, is mutated in 5%–10% of metastatic colorectal cancers." (PMID 36912150, 2023).
metastatic colorectal cancer (continued). "The combination of cetuximab plus avelumab has been also recently tested with promising clinical activity in RAS/BRAF wild type chemo-refractory metastatic colorectal cancer patients." (PMID 35346313, 2022). "Outcomes after metastasectomy for metastatic colorectal cancer (mCRC) vary with RAS and BRAF mutational status, but their effects on resectability and conversion rates have not been extensively studied." (PMID 35610367, 2022). "In patients with metastatic colorectal cancer, BRAF-mut portends a significantly worse prognosis, and is associated with both a lack of response to anti-EGFR therapy and a decreased resectability rate of recurrence after the initial resection of CLMs." (PMID 36013567, 2022). "BRAF testing should therefore be conducted routinely in Irish metastatic colorectal cancer patients, as it has the potential to guide therapeutic strategy in this small but important group of patients." (PMID 34877621, 2022). "The first-line chemotherapy for patients with RAS and BRAF wild-type metastatic colorectal cancer (mCRC) commonly involves cytotoxic regimens, such as FOLFOX and FOLFIRI, combined with epidermal growth factor receptor (EGFR) antibodies." (PMID 36439491, 2022). "Sidedness of primary tumor is a well-established prognostic marker and is predictive for anti-EGFR efficacy in RAS/BRAF wild-type metastatic colorectal cancer (mCRC) patients." (PMID 35158793, 2022). "Currently, a series of studies on anti-HER2 therapy drugs in RAS/BRAF WT metastatic colorectal cancer patients is underway, and encouraging results have been obtained." (PMID 36339570, 2022). "This study aimed to evaluate its safety, tolerability, pharmacokinetics (PK), and efficacy in patients with wild-type KRAS/NRAS/BRAF metastatic colorectal cancer (mCRC)." (PMID 36307775, 2022). "The BEACON trial is currently comparing doublet or triplet targeted therapy with standard therapy in patients with BRAF V600E metastatic colorectal cancer." (PMID 35267469, 2022). "Anti-epidermal-growth-factor-receptor (EGFR) monoclonal antibodies (mAbs) are of great significance for RAS and BRAF wild-type metastatic colorectal cancer (mCRC) patients." (PMID 36131281, 2022). "The aim of this study was to investigate the effects of baseline plasma AREG levels in KRAS, NRAS, and BRAF wild-type metastatic colorectal cancer (CRC) on treatment outcome with palliative first-line cetuximab + FOLFIRI chemotherapy." (PMID 34893673, 2021). "Previous clinical trials have demonstrated the potential efficacy of rechallenge with anti- epidermal growth factor receptor (EGFR) monoclonal antibodies (mAbs) for patients with RAS/BRAF V600E wild-type metastatic colorectal cancer (mCRC)." (PMID 34098908, 2021). "Few data regarding post-induction management following first-line anti-epidermal growth factor receptor (EGFR)-based doublet regimens in patients with left-sided RAS/BRAF wild-type metastatic colorectal cancer (mCRC) are available." (PMID 34778029, 2021). "Eligible patients aged ≥70 with unresectable metastatic, untreated, RAS/BRAF wildtype metastatic colorectal cancer will be randomised 1:1 to receive panitumumab alone or panitumumab plus infusional 5-fluorouracil." (PMID 34407800, 2021). "Herein, we report a case of wild-type RAS/BRAF metastatic colorectal cancer (CRC) with resistance to anti-EGFR monoclonal antibody and chemotherapy." (PMID 34888240, 2021). "Metastatic colorectal cancer (mCRC) harbors several mutations with different prognostic and predictive values; KRAS, NRAS, and BRAF mutations are the best known." (PMID 34988329, 2021).